RN7SL727P (RNA, 7SL, cytoplasmic 727, pseudogene)
Gene: Miscellaneous RNA gene on chromosome X (140,085,855 to 140,086,150, forward strand). Ensembl gene ENSG00000241248.
Homologues: Orthologues: chimpanzee Metazoa_SRP (98% identical), macaque Metazoa_SRP (90% identical), dog Metazoa_SRP (58% identical). Paralogues in human: RN7SL1 (84% identical), RN7SL2 (84% identical), RN7SL3 (83% identical), RN7SL126P (81% identical), RN7SL220P (81% identical), RN7SL664P (81% identical), RN7SL296P (80% identical), RN7SL408P (80% identical), RN7SL566P (80% identical), RN7SL478P (80% identical), RN7SL679P (80% identical), RN7SL709P (80% identical), and 703 more.